FLG (filaggrin)
Diseases named in the same sentence as FLG in open-access papers (continued):
Sharing a sentence is not in itself a finding about the gene and the disease.
Hyperkeratosis (7 papers, 2008 to 2025). Hyperkeratosis is a histopathological term defining a thickened stratum corneum and may be present in many different skin conditions, with many possible overlaps. "Filaggrin deficiency disrupts corneocyte differentiation and the formation of natural moisturizing factor, leading to hyperkeratosis due to water retention and increased transepidermal water loss." (PMID 40282340, 2025). "The severe clinical findings in affected PPK2 family members could possibly be a combined effect of variants AQP5 (NM_001651.4): c.103T>G (p.(Trp35Gly)) and FLG (NM_002016.2): c.1501C>T (p.(Arg501Ter)), which co-segregate with hyperkeratosis in the family." (PMID 36076978, 2022). "However, upregulated FLG reflects hyperkeratosis, while ALOX12B, ALOXE3, and KRT16 are wound-activated genes in the oral mucosa, suggesting an ongoing wound repair process." (PMID 34506598, 2021). "The mice develop the same morphological and histological changes including hyperproliferation and hyperkeratosis, and abnormal expression and subcellular distribution of K14, K6, filaggrin and loricrin, suggesting that CXCR3 related ligands are marginally important in phenotype development." (PMID 28569792, 2017). "We observed many HI features in our Abca12el12/el12 mice including severe hyperkeratosis, LB defects, absence of intercellular lamellae, aberrant filaggrin processing, neonatal death, defects in lipid metabolism, congenital contractures and the absence of skin barrier function." (PMID 18802465, 2008).
skin infection (7 papers, 2016 to 2024). An inflammatory process affecting the skin, caused by bacteria, viruses, parasites, or fungi. "FLG null mutations predispose individuals to microbial dysbiosis and reduced ability to control skin infections, resulting in S. aureus superinfections and a predisposition to eczema herpeticum." (PMID 38585273, 2024). "In the past decade, the multifunctional corneocyte protein filaggrin has emerged as essential for cutaneous barrier function, with various loss-of-function mutations associated with lifelong susceptibility to severe skin infection." (PMID 28081250, 2017). "Reduced FLG expression has also been correlated with an increased S. aureus colonization of epidermal skin models, and in children with AD, the presence of FLG mutations predisposed to recurrent skin infections." (PMID 31470558, 2019). "We evaluated skin infection with the current smallpox vaccine, ACAM-2000, in immunosuppressed mice with combined cutaneous deficiency in filaggrin and STAT3." (PMID 28081250, 2017). "However, Hirose and colleagues also showed that an arcA mutant was attenuated in mouse skin infection and this was attributed to an inability of the mutant to acquire alternative energy in the form of filaggrin-derived arginine." (PMID 36014103, 2022). "The association of FLG null mutation with AD and EH have demonstrated ethnic differences: In Asians, FLG P478 S and C3321delA are associated with increased risk to AD, the atopic march and recurrent skin infection; In African populations, FLG mutations are not common." (PMID 27777593, 2016).
breast carcinoma (6 papers, 2015 to 2023). "Second, compared to conventional breast cancer, somatic mutations in MUC17, FLG and NEBL were of much higher prevalence among EOBC patients." (PMID 32731431, 2020). "Preliminary validation of 3 potential markers (ECM1, MAST4 and filaggrin) identified was performed in breast cancer cell lines by Western blotting." (PMID 26544852, 2015). "Furthermore, extracellular matrix protein 1 (ECM1), microtubule-associated serine/threonine kinase family member 4 (MAST4), and Filaggrin (FLG) exhibit heightened levels in the urine of breast cancer patients." (PMID 38250812, 2023). "Moreover, ECM1, MAST4, FLG, and MAST4 are implicated as potential biomarkers for the preliminary indication of breast cancer presence." (PMID 38250812, 2023). "In breast cancer, non-invasive detection through urinary biomarkers, such as MMP9, NGAL, CD63, ECM1, MAST4, and Filaggrin, offers insights into disease progression." (PMID 38250812, 2023).
gastric cancer (6 papers, 2022 to 2025). A primary or metastatic malignant neoplasm involving the stomach. "Filaggrin (FLG) mutation led to increased gastric cancer sensitivity to 24 chemotherapeutic drugs, suggesting a potential protective factor." (PMID 37867602, 2023). "FLG mutations had been proved as a tumor-associated mutations in serval cancers, including gastric cancer, skin cutaneous melanoma, prostate cancer, and cervical cancer." (PMID 36923423, 2023). "Then we found that FLG mutations resulted in increased gastric cancer sensitivity to 24 chemotherapeutic drugs and small-molecule anticancer drugs, especially in LFM." (PMID 36046250, 2022). "We performed a series of analyses such as tumor mutational burden (TMB), immune infiltration, and copy number variation (CNV) analysis to evaluate the potential mechanism of filaggrin (FLG) mutation in gastric cancer." (PMID 36046250, 2022). "As in previous studies, the role of filaggrin in skin physiology and disease is well-established; we thus surmise that FLG gene mutation may also have a role in epidermal differentiation, morphogenesis, and homeostasis of gastric cancer cells." (PMID 36046250, 2022). "The FLG mutations resulted in increased gastric cancer sensitivity to 24 chemotherapeutic drugs." (PMID 36046250, 2022). "Although FLG and VCAN are less well explored in HER2+ BC, FLG mutations have been associated with higher tumor mutation load and immunogenicity in gastric cancer, while VCAN alterations have been linked to prostate cancer progression and docetaxel resistance." (PMID 41019979, 2025). "Next, we analyzed the functional enrichment pathways of the FLG-MT and FLG-WT groups in the TCGA-gastric cancer by GSEA." (PMID 36046250, 2022). "We collected the TCGA-gastric cancer containing clinical data and mutation data to explore the gene mutation and pathological mechanism of STAD using bioinformatic analysis, and we found that FLG gene mutations have an important impact on the clinical and biological characteristics of STAD." (PMID 36046250, 2022).
Pruritus (6 papers, 2019 to 2025). Pruritus is an itch or a sensation that makes a person want to scratch. "Intense pruritus leads to the behavior of scratching, which is an important symptom of AD associated with filaggrin (FLG)-regulated epidermis disruption." (PMID 32111037, 2020). "Pro-Filaggrin Complex, which is composed of a glucomannan derived from the yeast, Candida utilis, galactoarabinosa, and Niacinamide, reduces typical AD pruritus and its associated scratching." (PMID 30700045, 2019). "Individuals with filaggrin deficiency may derive benefit from future therapies targeting keratinocyte-immune crosstalk and neurogenic pruritus." (PMID 31641698, 2019). "We added to the moisturizing treatment a new Syndet cleanser, which is formulated to mitigate pruritus, induce the production of filaggrin, and reduce skin inflammation." (PMID 30700045, 2019).
sensitization (6 papers, 2014 to 2024). "This has been used as an argument for the role of FLG loss-of-function mutations as a predisposing factor for allergic sensitization after epicutaneous exposure to allergens." (PMID 25282568, 2014). "In contrast to filaggrin, claudins are highly expressed in the epithelium of airways and GI tract, thus, the downregulation of claudins could mediate a common dysregulation of the epithelial barrier function in these organs, potentially leading to allergic sensitization at various sites." (PMID 35844593, 2022).
squamous cell carcinoma (6 papers, 2015 to 2023). A carcinoma arising from squamous epithelial cells. "A case study showed that individuals with filaggrin mutation had an increased risk of squamous cell carcinoma (SCC), indicating a potential association between the development of SCC and filaggrin mutation." (PMID 37894374, 2023). "It has been shown that filaggrin may be expressed in subpopulations of oral squamous carcinomas and in cultivated squamous cell carcinoma (SCC-13)." (PMID 34834228, 2021).
cervical cancer (5 papers, 2021 to 2023). A primary or metastatic malignant neoplasm involving the cervix. "FLG mutations are strongly associated with cervical cancer and cutaneous melanoma and can serve as a biomarker for prognosis and treatment." (PMID 37024829, 2023). "In cluster 1/2, the incidence of FLG, BIRC6, and IGSF10 mutations were significantly higher, and it is reported that FLG contributes to the biological activity of barrier function and associates with the poor prognosis of cervical cancer." (PMID 37735483, 2023). "Genetic defects in filaggrin predispose women to HPV infection and increased cervical cancer mortality." (PMID 35869172, 2022).
hand eczema (5 papers, 2014 to 2023). A form of contact dermatitis characterised by inflammation, redness and itching of the hands. "The heterozygous loss-of-function mutation in the filaggrin gene, in combination with atopy, negatively affects the disease course of hand eczema." (PMID 36983235, 2023). "Moreover, more recent literature cites that filaggrin mutation(s) are associated with early onset, persistence, and/or an adverse disease course of hand eczema." (PMID 36983235, 2023). "In particular, the mutation(s) in the filaggrin gene may increase the risk of certain sub-type(s) of hand eczema due to the contribution toward a disrupted epidermal barrier, greater loss of hydration, inflammation, and exposure to environmental allergens." (PMID 36983235, 2023). "Filaggrin mutations vary in terms of prevalence among different ethnicities, which may explain why different ethnicities have different incidences and severity of hand eczema." (PMID 36983235, 2023). "Other morphological subtypes of hand eczema with obvious inflammation may lead to a secondary downregulation of filaggrin expression." (PMID 32333380, 2020). "In two other studies filaggrin expression in hand eczema biopsies was analyzed." (PMID 32333380, 2020).
metastatic melanoma (5 papers, 2020 to 2025). A melanoma that has spread from its primary site to another anatomic site. "Beyond E-cadherin, we observed enrichment of proteins that preferentially associate with nonpalmitoylated CTNND1, including filaggrin (FLG), plakophilin-1 (PKP1), and transglutaminase 1 (TGM1), all linked to poor clinical outcomes in metastatic melanoma." (PMID 41321310, 2025).
Netherton syndrome (5 papers, 2012 to 2021). Netherton syndrome (NS) is a skin disorder characterized by congenital ichthyosiform erythroderma (CIE), a distinctive hair shaft defect (trichorrhexis invaginata; TI) and atopic manifestations. "Interestingly, transgenic mice overexpressing Ela2 also exhibit a barrier defect, which probably results from excessive (pro-)filaggrin processing combined with alterations in lipid metabolism; similar changes in lipid metabolism are seen in the skin of Netherton syndrome patients." (PMID 32457102, 2020).
acne (4 papers, 2022 to 2025). An inflammatory process of the sebaceous glands which is characterized by comedones, nodules, papules and/or pustules on the skin. "PGC exhibited potent antibacterial efficacy against acne‐associated pathogens (Cutibacterium acne, MIC = 25 μg/mL), restored skin barrier integrity (filaggrin, +235%; loricrin, +261%), and sodium dodecyl sulfate (SDS)‐induced damage (85%)." (PMID 40762221, 2025). "P. acnes modulates keratinocyte differentiation by inducing integrin and filaggrin expression and aggravates local inflammation, thereby resulting in early-stage acne microcomedones and inflammatory lesions in acne vulgaris." (PMID 38792208, 2024). "Thus, FLG null mutations might favor the growth of Cutinobacterium acnes to an extent that allows bacterial competition but not to a level that provokes acne (i.e., dysbiosis, not infection)." (PMID 35628125, 2022).
allergic contact dermatitis (4 papers, 2016 to 2025). An inflammatory skin condition caused by an immune response to direct contact between the skin and an allergen. "It would be interesting to examine whether EPI-/- mice exhibit increased allergic contact dermatitis, because Filaggrin-null mice, which also have a defective barrier, display an enhanced cutaneous response to ovalbumin sensitization." (PMID 26763429, 2016).
contact dermatitis (4 papers, 2023 to 2024). An inflammatory skin condition caused by direct contact between the skin and either an irritating substance or an allergen. "Consistently, the filaggrin gene, which encodes a protein that is crucial for the function of the skin’s barrier, has recently been linked to an increased risk of developing chronic irritant contact dermatitis." (PMID 36769309, 2023). "Additionally, patients deficient in the FLG gene develop contact dermatitis at lower allergen exposure than patients carrying the FLG wild-type gene." (PMID 37685997, 2023). "Bilateral ovariectomy in mice resulted in reduced skin barrier function, decreased skin recovery after acute disruption, increased irritant contact dermatitis, and downregulated epidermal proteins, filaggrin and involucrin." (PMID 38675137, 2024).
diabetes (4 papers, 2013 to 2024). "Here, we examined whether loss-of-function mutations in FLG were associated with diabetes, IHD, stroke, and all-cause mortality by combining data from four Danish studies." (PMID 24367652, 2013).
eczema herpeticum (4 papers, 2014 to 2024). "Alternatively, it might represent a suboptimal, partially functional mechanism to compensate for the increased frequency of viral infections, including eczema herpeticum, seen in filaggrin-deficient subjects." (PMID 24880632, 2014).
ovarian carcinoma (4 papers, 2018 to 2023). A malignant neoplasm originating from the surface ovarian epithelium. "The tumor specificity of MUC12 and FLG is not strong, and the early diagnosis of MUC16 in ovarian cancer is not satisfactory." (PMID 37024829, 2023).
Arthritis (3 papers, 2008 to 2025). Inflammation of a joint. "They examined several mouse models of experimental arthritis and found that several, including CIA, had antibodies detected by first generation CCP assay based on citrullinated sequences from filaggrin." (PMID 27210478, 2016).
dental caries (3 papers, 2018 to 2023). The decay of a tooth, in which it becomes softened, discolored, and/or porous. "Mutations in the Fillaggrin Gene (FLG) may also be associated with the pathogenesis of dental caries, since it has an expression in oral mucosa." (PMID 29988222, 2018). "Oral mucosa of the defective FLG gene can also be prone to dryness and infection hence leading to dental caries." (PMID 35510248, 2022). "It is believed that a lack of filaggrin in the oral mucosa would increase a person's vulnerability to dryness and infections carried on by germs like Streptococcus mutans, the main cause of dental caries." (PMID 37234145, 2023). "Based in what is observed in filaggrin-deficient skin, it is reasonable that absence of filaggrin in oral mucosa promotes greater susceptibility to dryness and infections caused by microorganisms such as Streptococcus mutans, the most common agent of dental caries." (PMID 29988222, 2018).
eosinophilia (3 papers, 2021 to 2024). "Differently, extrinsic AD is characterized by high total IgE levels, eosinophilia, a personal or family atopic background and a greater rate of filaggrin gene mutations, and its endotype classically includes TH-2-TH-22 and TH-17 markers." (PMID 37834935, 2023). "In contrast to intrinsic AD, the extrinsic (80%) phenotype is characterized by high total and environmental serum IgE levels, eosinophilia, personal and family atopic background, and greater rate of filaggrin (FLG) mutation." (PMID 34947948, 2021). "The classic and more frequent extrinsic phenotype (80%) is characterized by high serum IgE levels, eosinophilia, personal and family atopic background, and greater rate of filaggrin (FLG) mutation, the latter being the strongest genetic risk factor for AD development." (PMID 39064029, 2024).
hepatocellular carcinoma (3 papers, 2021 to 2022). A malignant tumor that arises from hepatocytes. "FLG germline variants have been recently reported in around 16% of Taiwanese BC patients and 17% of hepatocellular carcinomas from Thailand." (PMID 35406420, 2022).
keloid (3 papers, 2022 to 2025). An irregularly shaped, elevated mark on the skin caused by deposits of excessive amounts of collagen during wound healing. "We performed immunohistochemical staining using anti-Filaggrin, anti-Protein Gene Product 9.5 (anti-PGP9.5), and anti-Cytokeratin 5 antibodies to analyse the nerve fibres extension into the epidermis in the peripheral regions of the anterior chest keloids." (PMID 40830367, 2025). "Moreover, several proteins that play a role in cell junctions were also downregulated in keloids, including EVPL, PPL, DSP, PKP1, PKP3, DSC1, DSG1, and FLG." (PMID 35435317, 2022).
keratoconus (3 papers, 2014 to 2023). A degenerative, structural disorder of the eye, characterized by a cone-shaped protrusion of the cornea. "VSX1 (Visual system homeobox 1), TIMP3, TGFBI, ZEB1, filaggrin (FLG) and several collagen genes, such as COL4A3, COL4A4 AND COL5A1, have been associated with keratoconus, while the distinct potential loci, which have been described, include 3p14-q13, 5q21, 5q32 and 14q11." (PMID 28932340, 2017). "Other candidate genes including SOD1, ZEB1, TGFB1, FLG, interleukin, and collagen may have a role to play in the pathogenesis of keratoconus and need further elucidations." (PMID 25254113, 2014).
keratosis pilaris (3 papers, 2009 to 2022). A form of dry skin characterized by hair follicles plugged by scale. "Keratosis pilaris was significantly associated with palmar hyperlinearity (p < 0.000, 95% CI 0.000–0.006, OR 4.664, 95% CI 2.072–10.496) and the filaggrin loss‐of‐function mutation 2282del4 (p < 0.000, 95% CI 0.000–0.009, OR 4.917, 95%CI 1.961–12.330)." (PMID 35616138, 2022). "The cellular and molecular mechanisms by which filaggrin deficiency results in skin features such as palmar hyperlinearity and keratosis pilaris remain to be defined." (PMID 19681860, 2009). "In addition, FLG mutations were associated with palmar hyperlinearity and keratosis pilaris significantly." (PMID 23152869, 2012).
lung adenocarcinoma (3 papers, 2018 to 2022). A carcinoma that arises from the lung and is characterized by the presence of malignant glandular epithelial cells. "The C3 immune subtype of lung adenocarcinoma exhibited longer survival, whereas the C1 subtype was associated with a higher mutation rate of MUC17 and FLG genes compared with other subtypes." (PMID 35354459, 2022).
Palmoplantar keratoderma (3 papers, 2017 to 2025). Abnormal thickening of the skin of the palms of the hands and the soles of the feet. "Cx26CK14-S17F/+ foot pad epidermis formed severe palmoplantar keratoderma, which expressed elevated levels of Cx26 and filaggrin." (PMID 28569788, 2017). "The c.1501C>T variant in the FLG gene cannot be a cause of PPK, although it might have a modifying impact on the phenotype, leading to more severe keratoderma, which also affects the skin on the face and body, as well as nails and hair." (PMID 36076978, 2022).
viral infection (3 papers, 2014 to 2022). "Differences between samples from controls and neonates with ongoing viral infection in several molecules (filaggrin, VEGF, RANTES (CCL5), HIF-1α, IL-17A and IL-1 β) were also observed, indicating an immune response associated with viral infection." (PMID 36482106, 2022).
X-linked ichthyosis (3 papers, 2013 to 2024). "Three patients had biallelic loss-of-function variants in FLG, whereas 6/11 males were affected by X-linked ichthyosis." (PMID 38791074, 2024).